MET (MET proto-oncogene, receptor tyrosine kinase)
Diseases named in the same sentence as MET in open-access papers (continued):
Sharing a sentence is not in itself a finding about the gene and the disease.
tumor (continued). "c-MET tracer 89Zr-onartuzumab kinetics were not influenced by 14.1 ± 5.2 ng/mL per gram tumor shed c-MET in MKN-45 xenografts at high tracer doses of 64 to 128 μg." (PMID 27602494, 2016). "Additionally, considering that loss of chromosome frequently occurred in many cancers can result in genomic chromosomal instability, it implies that the loss of the reference gene loci in the tumor may cause a false-positive elevated ratio of MET:AP3B1 in ddPCR, rather than high MET copy number." (PMID 26765781, 2016). "In the present study, we investigated the effects of c-MET inhibitors in OCCCs with in vivo as well as in vitro experiments including an orthotopic mouse model using an established cell line (RMG1) and a patient-derived tumor xenograft (PDX) model." (PMID 27917934, 2016). "Even though MGCD265 treatment significantly impaired tumor growth in all of the TNBC lines, complete growth inhibition after 3 weeks of treatment was only observed in the TNBC lines that had 4–5 MET copies and a positive growth trend can be observed in tumors without MET gene copy gain." (PMID 27655711, 2016). "Negative MET expression was shown for 132 (63.2 %) tumor tissue samples (28 (13.4 %) samples were scored as 0 and 104 (49.8 %) samples were scored as 1)." (PMID 26215852, 2015). "Three of the four initially FISH negative tumors showed a heterogeneous MET signal distribution pattern in the larger tumor section than in the TMA cores with a focal increase in MET gene copy numbers resulting in focal high level amplification." (PMID 25844809, 2015). "In CRC, c-MET protein expression was observed as in tumour cells, but was negative in inflammatory cells, endothelial cells, smooth muscle cells or fibroblasts." (PMID 26459369, 2015). "Tivantinib also induced apoptosis in both MET-negative tumor cells and genetically engineered cancer cells expressing a MET protein lacking the tivantinib-binding domain, suggesting that tivantinib acts independently of its ability to bind MET." (PMID 26123926, 2015). "MET can activate many of the same downstream signaling pathways as EGFR, such as ERK1/2 and PI3K/AKT; additionally, it promotes tumor growth by affecting proliferation, anti-apoptosis, invasion, and angiogenesis in several tumor types." (PMID 26319934, 2015). "MET amplification was observed in alectinib-refractory tumors, although tumor samples from before the alectinib treatment were not available." (PMID 25941796, 2015). "Negative MET expression was observed for 164 (78.5 %) tumor samples 53 (25.4 %) cases were scored as 0, and 111 (53.1 %) tumor samples were scored as 1)." (PMID 26215852, 2015). "Sawada and colleagues postulated that c-MET is involved in peritoneal adhesion and dissemination, but not tumour growth." (PMID 26138303, 2015). "Similarly, in a phase 2 trial, longer survival was found in patients who received rilotumumab plus ECX and had positive MET expression in tumor tissues than patients who received ECX alone and had positive MET expression in tumor tissues." (PMID 28536405, 2015). "Recently an additional TKI, cabozantinib, an inhibitor of multiple receptor tyrosine kinases, including RET, MET and VEGFR2, has been reported to induce immunogenic modulation, altering tumor-cell phenotype and sensitizing tumor cells to immune-mediated attack." (PMID 26579226, 2015). "Furthermore, the expression and location of c-MET and PIK3CA proteins were also studied by IHC in resected tumor tissues." (PMID 26334097, 2015). "Three of them (HOXA11, MET, BRAF) are potential oncogenes currently being observed for common copy-number gains in a meta-analysis of copy number alterations across a panel of different cancer cell lines and tumor samples." (PMID 26043758, 2015).
tumor (continued). "This study is the first to describe the in vitro activity of crizotinib in RMS tumours, this suggesting that this molecule may be a potential therapeutic agent that effectively controls ARMS growth by inhibiting ALK, MET and IGF1R pathways." (PMID 26445453, 2015). "Only one of these agents, cabozantinib, which is an inhibitor of multiple receptor tyrosine kinases, including RET, MET, and VEGRF2 has been reported to induce immunogenic modulation, altering tumor-cell phenotype and sensitizing tumor cells to immune-mediated attack." (PMID 26579226, 2015). "In two PDC cell lines with METex14del+ without concurrent MET amplification, tumor growths were profoundly inhibited by both MET tyrosine kinase inhibitors and a MET targeting monoclonal antibody-." (PMID 26375439, 2015). "In conclusion, miR-34c suppresses tumor growth and metastasis in NPC by targeting MET." (PMID 25611392, 2015). "In cases without MET amplification, we perform custom-designed and RT-PCR using mRNAs from tumor to detect METex14del transcripts." (PMID 26375439, 2015). "Among those 22 patients, 10 had positive IHC staining for MET (H-score: median 5, range 1–35), while none of the patients had positive phospho-MET staining on archival tumor tissue." (PMID 26123926, 2015). "In a phase I dose-escalation study, capmatinib was tested in 33 patients with confirmed c-MET-dysregulated advanced solid tumours, with HCC representing the commonest tumour type (45%), which were refractory to current therapy or for which effective therapy was lacking." (PMID 28943627, 2015). "From the perspective of tumor biology it is, therefore, not surprising that these neoplasms represent the only entity in which high level MET amplifications were found." (PMID 25844809, 2015). "Select tumor samples were evaluated by ISH for MET TOP2A, and ALK, with no genetic aberrations (i.e. amplification or rearrangement) detected." (PMID 26498363, 2015). "In HER2 amplified GEC cell lines, HGF-mediated MET activation is able to rescue tumor cells from EGFR/HER2 inhibition, an effect that could be abrogated by knockdown or pharmacologic inhibition of MET." (PMID 24930887, 2014). "However, in rare cases, tumor cells can express HGF, leading to an autocrine loop-type mechanism of activation of MET." (PMID 24930887, 2014). "PI3K is a key downstream signaling molecule in the HGF/MET pathway and significant synergy was observed when ARQ 197 was combined with either GDC-0980 or NVP-BEZ235 in suppressing MPM cell motility and growth and in vivo tumor development." (PMID 25221930, 2014). "Although the gene amplified subclonal area demonstrated a mean 41.8 copies of MET per nucleus, the remaining non-amplified tumor cells were also microdissected during processing for MS analysis based tumor cells observed by H&E staining." (PMID 24983965, 2014). "Based on these experiments, we concluded that MET was not required for CB42 tumor growth and metastasis." (PMID 25162504, 2014). "Further, we found that 9AA reduced the tumor burden in our NOD/SCID, MET-1 ATL mouse model." (PMID 24890041, 2014). "SST0116CL1 induced a relevant decrease of the protein levels of three typical client proteins (c-MET, AKT and CDK4) in GTL-16 tumor lysates and, at the same time, significantly increased the expression levels of the chaperone Hsp70, thus confirming that inhibition of Hsp90 function was achieved." (PMID 25096516, 2014). "Even though IHC found strong activation of the MET receptor in CB42, treatment of tumors by crizotinib, a MET inhibitor, did not inhibit tumor growth." (PMID 25162504, 2014). "Immunohistochemistry evaluation showed 43% of cases were c-MET negative and in 57% c-MET was observed at the tumor cell level." (PMID 24465403, 2014). "Multi-arm preclinical trials in MET-positive CRC cell lines and patient-derived xenografts revealed that long-lasting abolition of tumor growth could be achieved through MET inhibition, with or without concurrent interception of EGFR." (PMID 24811491, 2014).
tumor (continued). "Protein expression analysis showed that out of 107 analyzable cases, 46 cases (43%) were c-MET negative, and 61 cases (57%) were c-MET positive at the tumor cell level." (PMID 24465403, 2014). "Using genomic DNA extracts prepared from NSCLC archival tumor tissues, we failed to see any mutations in PAX8 genomic DNA (exons), while MET mutations were apparent (data not shown)." (PMID 24628993, 2014). "HGF/MET-induced MAPK signaling has been shown to be essential for proliferation, migration and invasion while the induction of AKT signaling promotes tumor cell survival." (PMID 24326130, 2013). "Given that tumor-stroma interaction via HGF–MET axis is involved in cancer metastasis, inhibition of MET signaling may be a pathogenesis-based anti-tumor strategy." (PMID 23296269, 2013). "Regardless of the presence or absence of MET mutation, stroma-secreted HGF plays a common role in tumor invasive growth." (PMID 23296269, 2013). "Such schemes may involve giving intermittent cycles of c-MET inhibitor, followed by VEGFR2 inhibitors, which would effectively result in locking up the c-MET inhibitors in the tumor cell compartment." (PMID 23484006, 2013). "MET decoy receptors are soluble forms of the cMET extracellular domain which compete with HGF and inhibit cMET dimerization; in vitro and in vivo mice models demonstrate suppression of HGF-induced tumor cell migration and metastasis." (PMID 23606971, 2013). "Interestingly, whereas cabozantinib completely blocked c-MET tyrosine phosphorylation in vitro in E98 cell cultures, phosphorylated c-MET was still present in remaining diffuse infiltrative tumor areas in treated mice." (PMID 23484006, 2013). "No tumor exhibited activation of hepatocyte growth factor receptor (c-MET) or insulin-like growth factor 1 receptor (IGF-1R)." (PMID 24204737, 2013). "It remains to be determined whether targeting the HGF/MET axis in MM and other HGF-expressing cancers will interfere with the tumor-induced immune dysfunction through the inhibition of IDO activity." (PMID 23232072, 2012). "Since the c-MET precursor is only expressed on the surface of cancer cells and not normal cells, this antibody is potentially tumor specific." (PMID 22511956, 2012). "Knockdown of ADAM-10, but not of ADAM-17, abolished MET down-regulation in different tumor cell lines, and compromised the DN30 ability to block MET signaling." (PMID 22973229, 2012). "There was no statistical difference between c-MET expression and age, sex, tumor differentiation, tumor location, tumor greatest dimension, distant metastasis and vascular invasion." (PMID 22640970, 2012). "The independence of the tumor signature on c-MET expression indicates that the tumor signature is not a consequence of the model-specific tumor-initiating lesion." (PMID 21949730, 2011). "We used the data derived from the c-MET model to generate signatures distinguishing tumor (TU) from adjacent non-tumor (AN) and wild-type (WT) normal tissues, and tested the prognostic power of these signatures in a data set from human HCC." (PMID 21949730, 2011). "The predictive power of the mouse-derived signatures likely stems from their tumor properties rather than c-MET-driven properties, and underscores the utility of mouse tumor models for identification of gene signatures relevant to human disease." (PMID 21949730, 2011). "There are many studies evaluating the expression of MET but a limited number with p-MET in human tumours and none of them have focused in SCLC." (PMID 21847116, 2011).
tumor (continued). "In addition to ESR1/ERα, the top-ranked genes selected by statistical cross-analyses were MET, FOS, SNCG, IGFBP4, and BCL2, which were subsequently validated in a larger set of tumor samples (from 17 control patients and 18 TF patients)." (PMID 18928543, 2008). "In addition, recent works have identified as MITF transcriptional targets genes such as the CDK2, the hipoxia induced factor HIF1A and the hepatocyte growth factor receptor MET, all of them presenting functions that contribute to tumor development." (PMID 18211678, 2008). "A common phenomenon of tumour formation is the amplification of proto-oncogenes such as HER2, EGFR, CCND1, and c-MET, which provide a selective advantage for tumour cell growth and survival through overexpression." (PMID 18349818, 2008). "The other three SCLC tumour tissues screened were immunostained negative for both of the p-MET antibodies." (PMID 17667909, 2007). "Analysis of both the IHC staining patterns of p-MET and Ki-67 indicates that the strong staining intensities do not coincide within the same tumours, suggesting that activated p-MET does not necessarily activate the cell proliferation pathway." (PMID 17667909, 2007). "Development of techniques of tumour tissue IHC with phosphoantibodies of c-MET and its downstream signal transducers molecules would enable the validation of inhibitor efficacy in the tumour tissue itself in future clinical studies of c-MET inhibitors." (PMID 17667909, 2007). "At this time point, mock-transfected cells do not form tumours, while wild-type MET-transfected cells form subcutaneous tumours in one out of five mice." (PMID 15785735, 2005). "All of the 19 RMS samples with no known translocation and all four of the PRMS tumours were found to express MET mRNA." (PMID 12865925, 2003). "Intravenously (i.v.)injected c-MET-positive (BJAB) as well as c-MET-negative (Daudi and Ramos cells) B-lymphoma cells formed tumours in SCID mice." (PMID 10487611, 1999). "However, several studies have since demonstrated a key role of HER3 in the activation of the PI3K/AKT signalling pathway in EGFR, HER2, and the hepatocyte growth factor receptor, MET, addicted tumours, and in particular, resistance to HER inhibitors such as cetuximab." (PMID 40940907, 2025). "MET activation by its ligand, hepatocyte growth factor (HGF), triggers a cascade of downstream signalling pathways, including the PI3K/AKT, RAS/MAPK, and STAT3 pathways, which are essential for driving oncogenesis, tumour progression, and metastasis (Reviewed in:)." (PMID 39774381, 2025). "While we did not directly assess tumor repolarization, it is reasonable to propose that inhibition of the c-MET/HGF axis may indirectly promote a shift in the TME." (PMID 41289612, 2025). "These exosomes carry a large number of tumor-related proteins, such as EGFR, HER2, PD-L1, MET and GPC1, which may be used as cancer-specific markers; ii) a high level of stability, making them suitable for long-term storage and the detection of clinical samples." (PMID 40612948, 2025). "Taken together, our results point out that the capability of producing anti-MET autoantibodies in the periphery is not necessarily dependent on MET expression in the tumor and may be beneficial for the patients." (PMID 40401526, 2025). "Upregulation of the HGF/MET signalling pathway significantly promotes OS cell proliferation, not only by directly modulating cell cycle progression but also by enhancing cell survival through activation of the PI3K/Akt pathway, thereby accelerating tumour growth." (PMID 40599602, 2025). "Additionally, the tumor microenvironment of 50% of HNSCC patients demonstrates an overexpression of HGF which has been reported to increase resistance to radiotherapy and to MET targeting tyrosine kinase inhibitor JNJ-38877605 via the association of PI3K-GAB1." (PMID 40560045, 2025).
tumor (continued). "Furthermore, an intersection analysis of the PamChip phosphorylation data with the gene expression results identified EGFR, MET, and FAK as the sole genes exhibiting upregulated expression at both the transcript and protein phosphorylation levels across the two TKI-resistant tumor cell line models." (PMID 41281943, 2025). "Preclinical data combining amivantamab (EGFR×c-MET BsAb) with pembrolizumab (anti–PD-1) in NSCLC showed increased infiltration of granzyme B–positive CD8+ T cells, expansion of central memory populations, and reduced tumor burden relative to either agent alone." (PMID 41262250, 2025). "In the same way, ALK and MET oncogenic fusions are not pathognomonic to a specific tumor type." (PMID 39409964, 2024). "Preclinical studies showed a reduced invasion and metastatic activity in mice with pancreatic NEN treated with CBZ: in particular, the simultaneous inhibition of VEGFR and MET pathways resulted in a smaller tumour mass and no metastases for CBZ-treated mice, compared to only anti-VEGF-treated mice." (PMID 37851242, 2024). "We propose that MET polysomy patients who benefited from the osimertinib and savolitinib combination may still have had sensitivity to osimertinib or may have had MET amplification in other tumor areas not uncovered by a single-site biopsy." (PMID 38276867, 2024). "To further explore the role of TWIST1 in MET driven NSCLC in vivo, we silenced TWIST1 in the MET exon 14 skipping mutant NSCLC cell line H596 and found that genetic inhibition of TWIST1 led to a significant decrease in tumor growth (68% reduction in mean tumor size)." (PMID 38485737, 2024). "Thus, MET-targeted ADCs can deliver cytotoxic agents directly to MET-expressing tumor cells, regardless of reliance on MET signaling." (PMID 39598385, 2024). "However, the one-armed 5D5 antibody does not exhibit anti-tumor activity in HGF-independent c-MET activation cases." (PMID 39664377, 2024). "However, in a phase II trial (NCT01954745) treating patients with advanced CCA, the unselective tyrosine kinase and MET inhibitor cabozantinib demonstrated no significant anti-tumor activity in an unselected patient population." (PMID 38730642, 2024). "Additionally, various pathways such as MAPK, PI3K/Akt, Wnt/β-catenin, hepatocyte growth factor (HGF)/c-MET, and JAK/STAT contribute to tumor cell phenotypic transitions, forming intricate feedback loops crucial for tumor survival, stemness, EMT, metastasis, and clonal potential." (PMID 39146202, 2024). "Consequently, ABBV-399 is a novel strategy to deliver a potent cytotoxin to c-MET-overexpressing tumor cells, facilitating cell killing independent of c-MET signaling." (PMID 39664377, 2024). "Finally, with respect to tumor hypoxia and angiogenic pathways, it is necessary to mention that hypoxia markers (HIF1α, carbonic anhydrase 9 (CAIX) and Glut1) are regulated by MET (hepatocyte growth factor receptor)." (PMID 38255995, 2024). "Moreover, single-cell analysis of circulating tumor cells has unveiled compelling insights into the effectiveness of HGF/c-MET inhibitors, such as rilotumumab (formerly AMG102) and compound A (a c-MET small molecule inhibitor), in curtailing cancer progression post-surgery." (PMID 39664377, 2024). "Studies have shown that MET gene amplification can often coexist with other tumor driver genes in NSCLC, such as EGFR and KRAS mutations and ALK and ROS1 fusions, indicating that MET gene amplification may not act as an intrinsic driver factor within tumors." (PMID 39582541, 2024). "This therapeutic benefit was independent of the tumor cells’ reliance on c-MET." (PMID 39664377, 2024). "These lines of experimental evidence demonstrate the critical role of HGF/MET and Wnt/β-catenin signaling co-activation in promoting tumor progression and inducing AR and SYN double-negative tumor cells, which is similar to what we have observed in PCa patient samples treated with current ADT." (PMID 38336745, 2024).